CD28 (CD28 molecule)
Diseases named in the same sentence as CD28 in open-access papers (continued):
Sharing a sentence is not in itself a finding about the gene and the disease.
autoimmune disease (continued). "The in vivo costimulation by CD28 for inducing autoimmune disease strictly requires an intact C-terminal proline motif that promotes lymphocyte-specific protein-tyrosine kinase (LCK) binding to the CD28 cytosolic tail." (PMID 19471607, 2008). "Furthermore, AGEs stimulate the proliferation of CD4(+)CD28(-) T cells, which play a role in autoimmune diseases." (PMID 40565966, 2025). "Next, we determined by the same methodology whether tTregs costimulated via TNFR2 or CD28 gain features of Tregs described in diseased human tissues, using published Treg gene signatures from cancer and autoimmune diseases." (PMID 38341270, 2024). "CD28, a costimulatory immune checkpoint molecule, enhances the activation of T cells, thereby ameliorating immune suppression or exacerbating the progression of autoimmune diseases." (PMID 38369521, 2024). "All these molecules exist as a soluble form and could interact with their receptors on monocytes: for example, sCTLA-4 could interact with CD80/86 and thereby prevent the binding with CD28 and T cell activation, as shown in autoimmune diseases." (PMID 39159266, 2024). "CD28 is widely recognized as the major costimulation pathway for naive T-cell activation, and the CD28/B7 pathway plays a central role in immune responses against pathogens, autoimmune diseases, and graft rejection (reviewed in the study of Kim and Choi)." (PMID 38046264, 2023). "Thus, the VPAC1 loss observed in CD4+CD28− T cells of these patients could be related with the fact that expanded senescent Th cells can produce large amounts of pro-inflammatory cytokines and also have cytotoxic potential in many inflammatory/autoimmune diseases." (PMID 33291545, 2020). "Our results suggest that individuals with the CT genotype on the CD28 rs1980422 locus showed high levels of susceptibility to ITP in the Chinese population, which confers the importance of CD28 rs1980422 in susceptibility to autoimmune diseases." (PMID 33584705, 2020). "The critical role of CD28 in induction of immune response was demonstrated in mice treated with CD28 antagonist, which induced antigen specific tolerance and prevented the progression of autoimmune diseases and organ graft rejection." (PMID 31181772, 2019). "CD28 is non-redundant for Tregs, as CD28-deficient mice have reduced Treg numbers and develop exacerbated autoimmune diseases, suggests a potential deleterious effect of CTLA4-Ig." (PMID 29973932, 2018). "Additionally, an increase in the frequency of CD28- T cells, which are resistant to immunoregulation and exhibit cytolytic and proinflammatory properties, is suggested to contribute to development of autoimmune diseases in premature immune aging." (PMID 30086167, 2018). "Accordingly, CD28 has been indicated as an important regulator of autoimmune diseases." (PMID 29163534, 2017). "Indeed, many reports showed the efficacy of anti-CD28 monoclonal antibodies in the treatment of autoimmune diseases and transplantation models." (PMID 28248972, 2017). "In conclusion, inhibiting the B7-1/CD28 signaling pathway is able to alleviate experimental lupus nephritis and provides an experimental basis for the therapeutic use of blocking the B7-1/CD28 signaling pathway in human lupus nephritis and other autoimmune disorders." (PMID 26096149, 2015). "Furthermore, blocking the CD28 pathway is used to treat a number of autoimmune diseases and to prevent allograft rejection, conversely this pathway can be stimulated to increase T cell immunity." (PMID 25347065, 2014). "TGN1412 was a CD28 superagonist antibody designed for patients suffering from autoimmune diseases." (PMID 22769234, 2012). "CD8+CD28- cells are more common in patients with autoimmune disease, and their increased effector functions may enhance autoimmune disease and inflammatory responses." (PMID 22136162, 2011). "Therefore, enhancing the efficacy of CAR-T by CD80 stimulation of CD28 may promote the progress of CAR-T immunotherapy in autoimmune diseases." (PMID 39575257, 2024).
autoimmune disease (continued). "However, pre-clinical trials assessing CD28SAbs for the therapy of autoimmune diseases reveal severe systemic inflammatory response syndrome in humans, thereby implying the existence of distinct signalling abilities between human and mouse CD28." (PMID 29540686, 2018). "Our data on the strong inhibitory effect exerted by treating primary T cells with ISA-2011B suggest that targeting the CD28/PIP5Kα signaling pathway may, therefore, provide an attractive therapeutic approach for the resolution of injurious inflammatory processes in autoimmune diseases." (PMID 28491063, 2017). "It has been reported that stimulation of Tregs with anti‐CD3/CD28, rapamycin, or retinoic acid increases their proliferation and enhances their regulatory capacity, which could improve their function in the treatment of autoimmune diseases or transplant rejection." (PMID 39097919, 2024). "To further understand the relationship between TNFR2- and CD28-costimulated tTregs and in vivo Tregs, we generated Treg signatures with high or low expression in NLT from cancer and autoimmune disease lesions." (PMID 38341270, 2024). "Recent studies have targeted the CD28/CTLA-4 cosignaling pathway to ameliorate transplant rejection and autoimmune diseases." (PMID 38342925, 2024). "CD8 (+) CD28 (−) Treg cells have been demonstrated to have beneficial effects in IBD and other autoimmune diseases, although their molecular mechanisms remain to be explored." (PMID 39555100, 2024). "Interestingly, CD28 also seems to play a central role in the regulation of IFNγ production, since several studies reported that CD4+ CD28- T cells secrete large amounts of IFNγ and have been associated with Th1-driven autoimmune diseases such as multiple sclerosis of rheumatoid arthritis." (PMID 35321714, 2022). "Occurrence of the SH2B3 missense change was associated with higher T-cell proliferation on PMBCs, stimulated with CD28 and CD3, suggesting a role of altered SH2B3 function in the pathogenesis of autoimmune disorders." (PMID 36123612, 2022). "It is a known fact that CTLA-4 Ig abatacept blocks CD28-mediated T cell activation by binding to the costimulatory B7 ligands CD80/CD86 on APCs, and it is currently used for RA and other autoimmune diseases." (PMID 32420329, 2020). "Our results provide novel insights on the role of CD28 and associated signaling mediators in IL-22 regulation in human CD4+ T cells and may provide the biological bases for the development of new therapeutic strategies to dampen inflammatory and autoimmune disorders." (PMID 33178223, 2020). "However, excessive activation of the B7-1/CD28 signaling pathway may induce autoimmune diseases." (PMID 26096149, 2015). "RA is a proinflammatory autoimmune disease attributed to failure of both CD4+CD25+ regulatory T (Tr) and CD8+CD28− suppressor T (Ts) cells to control autoreactive CD4+CD28+ Th1 and autoantibody-producing B cells." (PMID 23133752, 2012). "Studies on CTLA-4 and CD28 in nontumor fields other than oncology have mainly concentrated on autoimmune diseases, transplantation, and other domains, with limited research on immunosuppression." (PMID 38369521, 2024). "CD8+CD28− T cells have been found to be significantly increased in CMV positive compared to CMV negative in other autoimmune diseases." (PMID 32432117, 2020). "CD28 is a marker for antigen-induced stimulation; repeated TCR activation and presence of TNF-α and type-1 interferons increases the frequency of CD8+CD28– T cells and indicates a proinflammatory status in autoimmune disease." (PMID 30912766, 2019). "This suggests that dual antagonism of CD28 and ICOS could be particularly advantageous in autoimmune diseases where development of auto-antibodies contributes to pathogenesis since this process is particularly dependent on the contribution of Tfh cells." (PMID 32038630, 2019).
autoimmune disease (continued). "sCTLA-4Ig has been shown to modulate the CD28/CD80-CD86 pathway and inhibit T cell activation; in clinical trials, formulations of CTLA-4Ig have proved to be effective in the treatment of autoimmune diseases and allograft rejection." (PMID 24928993, 2014). "Pro-inflammatory cytokines, such as TNF or IL12A, the T-cell activation molecule CD28, the regulatory molecules IL10, TGFB1 or the adhesion molecules ITGA4 and ITGB1 have all been evaluated previously as therapeutic targets for autoimmune diseases, including MS." (PMID 18030350, 2007). "Abatacept, a CTLA-4Ig costimulatory blockade that interferes with CD28 on T cells binding to CD80/CD86 on APCs, has shown efficacy in clinical trials for RA (which has become one of the established treatments), psoriatic arthritis, and juvenile idiopathic arthritis, among other autoimmune diseases." (PMID 38567291, 2024). "As CD28 is the primary driver of Treg proliferation and CTLA-4 functions as the main brake, it implied that although the function of Helios− Tregs was unstable and decreased in autoimmune disease status, they might have more immunosuppressive function compared to Helios+ Tregs." (PMID 34054801, 2021). "However, in autoimmune diseases, the superior affinity of CTLA4 for its ligands led to the use of a CTLA4-immunoglobulin fusion protein (CTLA4-Ig) as an inhibitor of immune responses in vivo; the rationale being that it would bind to CD80 and CD86 and block their interaction with CD28." (PMID 26942414, 2017). "For instance, several mouse models of human inflammatory/autoimmune diseases, such as autoimmune diabetes in non-obese diabetic (NOD) mice, MS in experimental autoimmune encephalomyelitis (EAE) mice or systemic autoimmune disorders have evidenced the relevance of CD28 co-stimulatory signals." (PMID 31068940, 2019).
melanoma (77 papers, 2010 to 2026). A malignant, usually aggressive tumor composed of atypical, neoplastic melanocytes. "In melanoma, we identified an 8-gene signature (CD28, CD80, CD86, CTLA4, FAS, IFNG, IL10, and IL12A) associated with survival." (PMID 42216340, 2026). "This tandem single-chain variable fragment antibody is designed to target human CD28 and the melanoma/glioblastoma-associated cell surface chondroitin sulfate proteoglycan 4 (CSPG4)." (PMID 26469402, 2015). "Interestingly, the melanoma resistance of mice treated with LPPC/MP/CD28 complexes would be reversed to susceptible after administration with LPPC/MP/CTLA4 complexes." (PMID 36691089, 2023). "In fact, the risk of death due to melanoma was significantly increased in patients with CD28 abs." (PMID 23483974, 2013). "In line with this hypothesis, Bouwhuis and co-workers found a reduced PFS in melanoma patients with polymorphisms of the CD28 gene." (PMID 23483974, 2013). "Cohorts of WT, Cd28−/−, Carmil2−/−, Carmil2QE, and Carmil2QECd28−/− mice were injected subcutaneously with the syngeneic mouse melanoma tumor BRAFV600EPtgs−/− and monitored for tumor growth." (PMID 40402149, 2025). "In this proof-of-concept study, we demonstrate that anti-CD28-IST can selectively activate and expand polyfunctional cytotoxic CD8+ T cells from the naive repertoire, targeting the HIV-associated SL9 or melanoma-associated MART-1 epitopes." (PMID 40762498, 2025). "For comparison, unstimulated PBMC, PBMC stimulated with anti-CD3/CD28 beads for 72 hours, and blood and tumor-infiltrating lymphocytes from melanoma patients were also stained." (PMID 40589546, 2025). "At the protein level, Fgl2 cytokine was induced in CD8+ TIL from digested melanoma patient tumor tissue upon stimulation with anti-CD3/CD28." (PMID 38902261, 2024). "Consistently, with the strong interaction of the RONC-aH2 antibodies with melanoma MTP, the CD28-OX-40-HER2-specific CAR-T/NK cells were able to effectively lyse the HER2-positive melanoma cell line." (PMID 37761005, 2023). "When viewed in combination, these studies demonstrate that melanoma lung metastasis is associated with significantly suppressed expression of T cell co-stimulators including ICOS, ICOSL and CD28." (PMID 36618349, 2022). "This is in contrast to the “Th2-like Tregs” recently reported in melanoma that were shown to produce more Th2 cytokines than the other Tregs when activated in vitro with anti-CD3/CD28 beads." (PMID 36107619, 2022). "MRP1/CD28 bsApt showed increased accumulation at MRP1+ melanoma cancer cells (enriched population) compared with the parental melanoma cells, as measured by RT-PCR of disaggregated tumor." (PMID 35141049, 2022). "CD28‐mediated costimulatory pathways play a significant role during the differentiation of functional tumor‐specific CD8+ T‐effector cells and CD28 inexpression in patients suffering from melanoma will result in pulmonary metastases." (PMID 32902664, 2021). "CD28 expression is declined on metastatic melanoma cells while its expression shows an increase in CD4+ lymphocytes that are migrating toward tumors." (PMID 32902664, 2021). "All CD40L:CD28 CSPs showed strong induction of surface expression when the melanoma cell line was pretreated with CD40L antibody before it was used in the co-culture." (PMID 34912334, 2021). "Enhanced in vivo anti-tumor activity and cytokine production was also found in human MART-1 TCR T cells expressing a CSR based on TIGIT (TIGIT:CD28) in a human melanoma xenograft mouse model." (PMID 32570906, 2020). "In ACT of melanoma patients, data from our center (unpublished) and others have shown that high CD28 expression is a positive predictor of in vivo activity in TIL-based ACT." (PMID 32547707, 2020). "CD28Aptvax made of irradiated tumor cells coated with the CD28-agonistic aptamer attached to MRP1 elicits a strong tumor- cell immune response against melanoma tumors reducing tumor growth." (PMID 26992239, 2016).
melanoma (continued). "Tetramer+ human T cells purified from hu-mice were stimulated for 5 days with anti-huCD3/CD28 microbeads, and their cytotoxicity against melanoma cells was assessed by 51Cr-release assay." (PMID 26824989, 2016). "In this work we show a clinically feasible strategy to convert in situ the own tumor into an endogenous vaccine by coating the melanoma cancerous cells with CD28 costimulatory ligands." (PMID 26992239, 2016). "Regarding immunological parameters, a significant increase in T-cell ICOS expression (costimulatory molecule, third member of the CD28/CTLA-4 family) following ipilimumab treatment was found in melanoma patients who experienced disease control." (PMID 26337719, 2015). "We found a significant correlation between the occurrence of CD28 abs and death of melanoma patients during the observation period." (PMID 23483974, 2013). "We found a significantly higher prevalence of CD28 abs in the group of melanoma patients and patients with viral hepatitis than in the other control groups investigated." (PMID 23483974, 2013). "We therefore conducted this retrospective study in which we investigated the prevalence of CD28 serum abs in melanoma patients in comparison to several control groups." (PMID 23483974, 2013). "We investigated 230 melanoma patients for the occurrence of CD28 antibodies and the effect of the latter on overall and progress-free survival." (PMID 23483974, 2013). "We have previously reported that many CD8+ TIL down-regulate CD28 expression after the REP and that these cells became hyporesponsive to re-stimulation with melanoma antigens such as MART-1 and were more susceptible to cell death." (PMID 23560068, 2013). "Therefore, CARMIL2-CARD11-mediated CD28 signals were necessary and sufficient to eradicate the BRAFV600EPtgs−/− melanoma tumor implanted in Carmil2QECd28−/− mice." (PMID 40402149, 2025). "SK-MEL-30 melanoma cell line was co-cultured with HD-derived T cells in two culture variants: (i) T cells were exposed only to the examined peptides, or (ii) T cells were simultaneously stimulated with CD3/CD28 mAb and exposed to the tested compounds." (PMID 38835768, 2024). "Interestingly, the CD8+PD1+CD28− T-cell subset showed the highest polyfunctionality in each melanoma, NSCLC, and PDAC cancer patients." (PMID 37898752, 2023). "By taking advantage of a panel of CD8+ Ag-specific (Melan-A+ or gp100+) T-cell clones isolated from the peripheral blood of melanoma patients, we recently reported that the inhibitory effect of PD1 is associated with the co-expression of CD28, consistent with earlier studies." (PMID 37898752, 2023). "CD40L:CD28-transduced TCR-T58 T cells were co-cultured with the melanoma tumor cell line (SK-Mel23), which provides the activation stimulus through the TCR-peptide/MHC interaction (HLA-A2/tyrosinase, which is the ligand for TCR-T58) and expresses CD40 endogenously." (PMID 34912334, 2021). "To investigate the mechanism of action of PDI-1, we analyzed its binding to PD-1 and PD-L1 proteins in vitro and its ability to rescue TCR/CD28-dependent activation of T cells ex vivo and in vivo using melanoma and non-small-cell lung cancer (NSCLC) cell lines and mouse tumor models." (PMID 34054817, 2021). "Based on the results reported by Marco, the upregulated expression of CD28 correlated with a better benefit in patients with malignant melanoma treated with ipilimumab, indicating that CD28 can serve as a prognostic factor in melanoma." (PMID 34367975, 2021). "Studies in melanoma and lung cancer mouse models suggest that NK responses could be mediated through the CD28/CTLA-4:B7–1/B7–2 system, by direct inhibition of NK IFN-γ production." (PMID 31395100, 2019). "A study performed to investigate the response of tumor-specific CTLs to a therapeutic combination of interferon-γ-inducible protein-10 and melanoma TRP2-specific CD8+ CD28+ T cells embedded inside folate altered chitosan nanoparticles, showed an inhibition of melanoma cells in vivo." (PMID 31652460, 2019).